CHL1 (cell adhesion molecule L1 like)
Description:
Extracellular matrix and cell adhesion protein that plays a role in nervous system development and in synaptic plasticity. Both soluble and membranous forms promote neurite outgrowth of cerebellar and hippocampal neurons and suppress neuronal cell death. Plays a role in neuronal positioning of pyramidal neurons and in regulation of both the number of interneurons and the efficacy of GABAergic synapses. May play a role in regulating cell migration in nerve regeneration and cortical development. Potentiates integrin-dependent cell migration towards extracellular matrix proteins. Recruits ANK3 to the plasma membrane (By similarity).
Synonyms: CALL; L1CAM2; FLJ44930; MGC132578
Tractability: Antibody: UniProt places it where antibodies can reach, with medium confidence; UniProt predicts a signal peptide or a membrane-spanning region; its Gene Ontology location is reachable by antibodies, with medium confidence. PROTAC: ubiquitination databases record sites on it; its protein half-life has been measured.
Gene: Protein-coding gene on chromosome 3 (196,763 to 409,417, forward strand). Ensembl gene ENSG00000134121.
Subcellular location: Cell membrane; Secreted, extracellular space, extracellular matrix (Processed neural cell adhesion molecule L1-like protein)
Pathways (Reactome):
Developmental Biology: CHL1 interactions
Gene Ontology:
Molecular function: identical protein binding; protein binding; protease binding
Biological process: cell adhesion; signal transduction; negative regulation of neuron apoptotic process
Cellular component: extracellular exosome; membrane; neuron projection; apical part of cell; dendrite; plasma membrane
Genetic constraint (gnomAD): Loss-of-function variants: 47 observed, 88.41 expected, observed/expected ratio (o/e) 0.53, 90% interval 0.42 to 0.68. The upper end of that interval is the gene's LOEUF score, 0.68, which puts it in group 2 of 6, group 1 being the genes least tolerant of losing a copy. Missense variants: 1,373 observed, 1,130.9 expected, observed/expected ratio (o/e) 1.21, 90% interval 1.16 to 1.27. Synonymous variants: 459 observed, 395.64 expected, observed/expected ratio (o/e) 1.16, 90% interval 1.07 to 1.25.
Homologues: Orthologues: chimpanzee CHL1 (99% identical), macaque CHL1 (97% identical), dog CHL1 (92% identical), pig CHL1 (91% identical), rabbit CHL1 (87% identical), rat Chl1 (86% identical), mouse Chl1 (84% identical), guinea pig CHL1 (81% identical), zebrafish chl1a (44% identical). Paralogues in human: NRCAM (41% identical), L1CAM (38% identical), NFASC (35% identical), CNTN2 (23% identical), CNTN4 (23% identical), CNTN3 (23% identical), CNTN6 (22% identical), CNTN5 (22% identical), CNTN1 (22% identical), ROBO2 (18% identical), PTPRQ (17% identical), ROBO1 (17% identical), and 24 more.
Diseases named in the same sentence as CHL1 in open-access papers:
CHL1 is named in the same sentence as 164 diseases in open-access papers, as found by Europe PMC text mining. Sharing a sentence is not in itself a finding about the gene and the disease. The quoted sentences say what the papers report.
schizophrenia (20 papers, 2010 to 2025). A major psychotic disorder characterized by abnormalities in the perception or expression of reality. "Close homolog of L1 (CHL1) gene dysregulation is associated with schizophrenia, so CHL1-deficient mice are utilized as a model of schizophrenia-like deficits, including interval timing and spatial memory impairments." (PMID 39769070, 2024). "The CHL1 gene is located on chromosome 3 at 3p26.1, a region which contains genes that are suggested to be associated with schizophrenia." (PMID 38025382, 2023). "The cell adhesion molecule close homolog of L1 (CHL1) contributes to dopaminergic system development, and CHL1 and the dopamine receptor D2 (D2R) are associated with mental disorders like schizophrenia, addiction, autism spectrum disorder and depression." (PMID 38025382, 2023). "Mutations in the coding region of CHL1 are involved in the etiology of schizophrenia in both Chinese and Japanese populations." (PMID 29089868, 2017). "CHL1 dysfunction has been implicated in abnormal thalamocortical circuitry, schizophrenia and autism." (PMID 29089868, 2017). "As a candidate gene for human schizophrenia and mental deficiency, CHL1 is relevant to learning behavior and reorganization of the frame of thinking." (PMID 27506765, 2016). "Three loci, including DPP10 on chromosome 2q14.1 and two genes in close proximity on chromosome 3p26.3, CNTN4 and CHL1, both encoding cell adhesion molecules, confer very strong susceptibility to autism, schizophrenia, and related disease." (PMID 23185133, 2012). "We have deliberately chosen conditions, which are close to those in diseased or highly stressed organisms, since mutations in CHL1 are associated with stress related disorders such as schizophrenia." (PMID 20711454, 2010). "The etiology of schizophrenia, a disease linked to mutations in the CHL1 gene in humans, not only includes a genetic predisposition but also an environmental underpinning." (PMID 20711454, 2010). "L1 and CHL1 are more studied and the most likely associated with schizophrenia." (PMID 41573035, 2025). "Moreover, CHL1 is implicated in mental retardation and psychiatric disorders, such as schizophrenia and autism spectrum disorders." (PMID 38025382, 2023). "Cell adhesion molecule close homolog of L1 (CHL1) has an important role in the development and regeneration of the nervous system, and is linked to pathologies, such as mental retardation or schizophrenia." (PMID 34357353, 2021). "Regulation of DNMT3A depends on miR-29 expression pattern in postnatal brain during lifespan so that downregulation of miR-29 associated with increased CH methylation in genes such as CHL1, FZD3, and SOX5 which are associated with schizophrenia." (PMID 38705955, 2024). "The sex-specific behavioral differences in CHL1−/− mice and CHL1’s implication in schizophrenia and autism spectrum disorders suggests that CHL1 participates in sex-dependent regulation of DA-dependent pathways in the dorsal and ventral striatum." (PMID 38025382, 2023). "Variations in the NrCAM gene have been implicated in autism and schizophrenia, while mutations in the CHL1 (CALL) gene are linked to intellectual disability, schizophrenia, and autism." (PMID 33585481, 2021). "In humans, mutations in CHL1 (referred to as CALL) are associated with reduced intelligence, mental retardation and occurrence of schizophrenia." (PMID 20711454, 2010). "Like L1, mutations of close homolog of L1 (CHL1, designated as ‘CALL’ in humans) are linked to neurological disorders that include psychiatric and other manifestations, including mental retardation, schizophrenia, and autism." (PMID 36411762, 2022). "In addition, some studies have suggested that CHL1 is a candidate gene for schizophrenia." (PMID 41573035, 2025).
breast cancer (18 papers, 2011 to 2025). A primary or metastatic malignant neoplasm involving the breast. "Similar results have been shown for breast cancer cells in which CHL1 deficiency led to tumor formation, and a knockdown of CHL1 expression led to increased proliferation and invasion." (PMID 32284790, 2020). "The CHL1 gene encodes a cell-adhesion molecule proposed as being a putative tumour-suppressor gene in breast cancer (BC)." (PMID 28178655, 2017). "Furthermore, knockdown of CHL1 expression causes increased proliferation and invasion in breast cancer cells." (PMID 32775417, 2020). "Interestingly, besides its putative tumor suppressor functions in early tumor development, repression of CHL1 has been shown in a cancer profiling array study to be associated with local tumor invasion in ovarian, colon, and breast cancer." (PMID 27096627, 2016). "CHL1, a potential tumor suppressor gene, was found to be downregulated in expression and to show hypermethylation, in line with a recent report of its high association with early preinvasive growth of breast cancer through facilitating tumor growth." (PMID 25137136, 2014). "Using this methodology, we identified nine proteins—FN1, VWF, PRG4, MMP9, CLU, PRDX6, PPBP (CXCL7), APOC1, and CHL1—that were robustly quantified in serum and showed statistically significant differences between breast cancer patients and healthy controls." (PMID 40940928, 2025). "Conversely, increased expression of NrCAM or CHL1 (a member of a homologous family) is correlated with better prognosis in prostate and breast cancer, both of which are hormone-related malignancies." (PMID 35388173, 2022). "Studies have reported that CHL1 promotes breast cancer and esophageal squamous cell carcinoma cells proliferation." (PMID 34718336, 2021). "Alterations of CHL1 have been correlated with several tumour entities and have been suggested to function as tumour biomarkers e.g. in breast cancer." (PMID 30964915, 2019). "Recently, it has been reported that CHL1 expression is shut-off by hypermethylation and that this epigenetic alteration is an independent prognostic factor in breast cancer and colorectal cancer." (PMID 29899830, 2018). "CHL1 is involved in cancer growth and in the metastasis of different human cancers, including colon and breast cancers." (PMID 22532847, 2012). "In total, a statistically significant decrease of CHL1 expression was found in breast cancer - 71% (45 of 63 cases), colon - 48% (23 of 48), rectum - 50% (14 of 28), thyroid - 69% (11 of 16), kidney - 75% (21 of 28) and small intestine – 67% (6 of 9) cancers." (PMID 21408220, 2011). "In human breast cancer, CHL1 knockdown enhanced tumor cells proliferation and invasion." (PMID 34718336, 2021). "Therefore, CHL1 may be a putative tumor suppressor gene in breast cancer and other common cancers." (PMID 29507648, 2018). "Although CHL1 functions as a putative tumor suppressor during primary tumor growth and is silenced to facilitate in situ tumor growth, re-expression of CHL1 on the edge of the tumor mass may promote local invasive growth and enable further metastatic spread in ovary, colon and breast cancers." (PMID 29089868, 2017). "3p would include TGFBR2, CNTN4, and CHL1 (reported for colorectal cancer) and CNTN6 (for breast cancer), as well as FHIT, ROBO1-GRE1 and SETMAR-LRRN1." (PMID 26247464, 2015).
neuroblastoma (17 papers, 1998 to 2024). Neuroblastoma (NB) is the most common solid, extracranial childhood tumor. "CHL1 and NrCAM expression was associated with low-grade pediatric neuroblastoma." (PMID 31989042, 2019). "CHL1 is a novel candidate tumor suppressor in neuroblastoma, and its associated pathways may represent a promising target for future therapeutic interventions." (PMID 29899830, 2018). "Another study documented that CHL1 regulates neuroblastoma cells’ proliferation and differentiation by inhibiting the MAPK signaling pathway." (PMID 34718336, 2021). "Thus, expression of CHL1 may be associated with high risk, immature neuroblastoma." (PMID 31989042, 2019). "Conversely, low CHL1 gene expression in 417 neuroblastoma samples was significantly correlated to a reduced overall survival." (PMID 31989042, 2019). "We therefore studied the expression of CHL1 and NrCAM according to the course of disease in children with neuroblastoma." (PMID 31989042, 2019). "CHL1 and NrCAM expression levels were histologically assessed by tissue microarrays from surgically resected neuroblastoma specimens of 56 children." (PMID 31989042, 2019). "We therefore determined the expression of CHL1 and NrCAM by immunohistochemistry in a neuroblastoma tissue microarray and correlated it to the individual course of disease." (PMID 31989042, 2019). "CHL1 expression as well as clinical, pathologic and molecular characteristics of the analysed neuroblastoma tissue samples." (PMID 31989042, 2019). "In the present study, the protein expression of CHL1 and NrCAM in pediatric neuroblastoma in correlation to clinical and survival data were analyzed." (PMID 31989042, 2019). "Over-expression of CHL1 induced neurite-like outgrowth and markers of neuronal differentiation in neuroblastoma cells, halted tumor progression, inhibited anchorage-independent colony formation, and suppressed the growth of human tumor xenografts." (PMID 29899830, 2018). "Previous report also revealed that miR-21 promotes the propagation and invasiveness of neuroblastoma cells by suppressing CHL1." (PMID 30134821, 2018). "Our findings demonstrate unambiguously that CHL1 acts as a regulator of proliferation and differentiation of neuroblastoma cells through inhibition of the MAPKs and Akt pathways." (PMID 29899830, 2018). "Expression of CHL1 as well as NrCAM has already been studied in neuroblastoma before." (PMID 31989042, 2019). "CHL1 was expressed in 9% and NrCAM in 51% of neuroblastoma tissue samples." (PMID 31989042, 2019). "Moreover, some researches verified that miR-21 targeting CHL1 to inhibit the neuroblastoma cell growth." (PMID 30134821, 2018). "Here we have used two inducible cell models to analyze the impact of CHL1 on neuroblastoma biology." (PMID 29899830, 2018). "We found that low CHL1 expression predicted poor outcome in neuroblastoma patients." (PMID 29899830, 2018). "In a previous study, we demonstrated that CHL1, the neuronal cell adhesion molecule close homolog of L1, acts as a tumor suppressor in human neuroblastoma (NB), a still highly lethal childhood malignancy, influencing its differentiation and proliferation degree." (PMID 33326488, 2020).
melanoma (15 papers, 2005 to 2024). A malignant, usually aggressive tumor composed of atypical, neoplastic melanocytes. "Alterations in CAM expression (including CHL1) and functions have been implicated in development of different tumor types, for example, melanoma, ovary, prostate and colon cancer." (PMID 21408220, 2011). "Recent reports link L1 expression to melanoma metastasis and ovarian and uterine carcinomas associated with poor clinical outcome but, regulation of Chl1 in lung cancers is novel and may act as coreceptor for integrin and growth factors." (PMID 19812696, 2009). "Data showed that the restoration of Fhit expression significantly affected the proliferation of melanoma cells, such as Colo38 and CHL-1." (PMID 36289813, 2022). "We first used CRISPR/Cas9 genome editing to knockout (KO) the TPCN2 gene in CHL1 and B16-F0 (murine primary melanoma) cell lines." (PMID 32846966, 2020). "To study the role of TPC2 in melanoma tumourigenesis and metastasis, we generated a CHL1 TPC2 KO cell line, CHL1 cells being a model of human amelanotic melanoma and derived from a metastatic site." (PMID 32846966, 2020). "Some of these genes were also described in different works regarding UM, while two of them (CHL1 and IL12RB2) were also found to be hypermethylated with low expression in invasive malignant melanoma cells; in particular, CHL1 is in an hypermethylated region on 3p in TCGA class 2 UMs." (PMID 38339073, 2024). "In melanoma cells, mTORC2 purified from A375(BRAFV600E) also showed lower enzyme activity compared to that purified from CHL1(wild-type BRAF)." (PMID 22880048, 2012). "According to Oncomine preliminary microarray expression data along with the prevalent CHL1 down-regulation in several tumors (RCC, lung SCC, colon ADC), the overexpression of CHL1 was found in melanoma." (PMID 21408220, 2011). "In the case of melanoma (MEL), high novelty targets are SPPL2A, CHL1, AP4E1, SECISBP2L, and COPS2." (PMID 34570764, 2021). "CJM, HMCB, and CHL1 also lacked mutations in BRAF, NRAS, or NF1, but these cell lines had similar FGA and mutational burden relative to other melanoma cell lines as well as tumors." (PMID 29383127, 2017). "The triple wild type melanoma cell lines compared in this study have poor correlation with tumors by copy number per gene with mean Pearson r values between 0.22 for HS940T and −0.14 for CHL1." (PMID 29383127, 2017). "To analyze and compare the tumour progression between two models of melanoma (WT vs. TPC2 KO) and elucidate the role and the impact of the two-pore channel 2 (TPC2) gene in tumour growth on melanoma cells in vivo, we subcutaneously injected B16 and CHL-1 WT or TPC2 KO cells into mice." (PMID 38104117, 2023).
cervical cancer (12 papers, 2014 to 2025). A primary or metastatic malignant neoplasm involving the cervix. "Among the microRNAs induced by calcitriol, miR-590 stands out as the only one with evidence of promoting cervical cancer cell growth and invasion by targeting CHL1." (PMID 40168262, 2025). "CHL1 was down-regulated in colon, stomach, bladder, or pancreatic cancer but upregulated in lung, liver prostate, and cervix cancers." (PMID 31989042, 2019). "Subsequently, it has been suggested that miR-590-5p acts as an oncogene by targeting CHL1 gene and promotes cervical cancer proliferation." (PMID 29899830, 2018). "MiR-10a, which targets CHL1, promotes cell growth, migration and invasion in human cervical cancer cells." (PMID 29899830, 2018). "In cervical cancer, miR-10a-5p promotes cell colony formation, migration and invasion by targeting CHL1." (PMID 29615098, 2018). "Knocking down CHL1 expression by miR-10a increased colony formation activity, migration and invasion of human cervical cancer cells, whereas over-expression of CHL1 abolished the effects of miR-10a." (PMID 29089868, 2017). "As for CHL1 gene, its negative regulation by miR-10a promoted cell growth, invasion and migration in cervical cancer cells." (PMID 24475022, 2014). "Current study had supported a significant role for CHL1 gene in the growth, migration and invasion of human cervical cancer cells." (PMID 24597767, 2014). "In cervical cancer, miR-590-5p was proven to facilitate tumor viability by inhibiting CHL1." (PMID 36304989, 2022). "Moreover, it has been shown that miR-590-5p can exert oncogenic activity in cervical carcinoma by targeting the CHL1 gene." (PMID 33681295, 2021). "Furthermore, an increase and decrease of miR-10a and CHL1, respectively, was shown in cervical cancer tissue versus normal tissue." (PMID 25192291, 2014). "In the same step of cervical cancer development, CIN 1, miR-10a is up-regulated and negatively modulates the cell adhesion molecule L1-like (CHL1)." (PMID 25192291, 2014). "miR-590-5p is up-regulated in human cervical cancer and promotes cervical cancer cell growth, cell invasion and colony formation by negatively regulating CHL1 at the posttranscriptional level." (PMID 29089868, 2017).
Intellectual disability (11 papers, 2011 to 2025). "Previous studies suggested CHL1 as a dosage-sensitive gene with a major role in intellectual disabilities." (PMID 32028920, 2020). "In mice, functional studies showed that the haploinsufficiency of Chl1 gene in the developing brain results in cognitive deficits suggesting that the CHL1 gene at 3p26.3 is a candidate for an autosomal form of intellectual disability." (PMID 26279679, 2015). "The finding of a balanced translocation disrupting the gene CHL1 in an individual affected by non specific mental retardation further supports this suggestion." (PMID 21457564, 2011). "Moreover, studies of mice have revealed that CHL1 is a prime candidate gene for a dosage-sensitive autosomal form of mental retardation." (PMID 27354858, 2016). "In addition the CHL1 gene, mapping at 3p26.3 distally to CRBN and CNTN4, was proposed as candidate gene for a non specific mental retardation because of its high level of expression in the brain." (PMID 21457564, 2011).